LINC02076 (long independently transcribed non-coding RNA 2076)
Synonyms: FLJ35934
Gene: Long non-coding RNA gene on chromosome 17 (18,411,150 to 18,414,388, forward strand). Ensembl gene ENSG00000220161.
Diseases named in the same sentence as LINC02076 in open-access papers:
LINC02076 is named in the same sentence as 2 diseases in open-access papers, as found by Europe PMC text mining. Sharing a sentence is not in itself a finding about the gene and the disease. The quoted sentences say what the papers report.
cancer (1 paper, 2022). A tumor composed of atypical neoplastic, often pleomorphic cells that invade other tissues. "The expression of AL356599.1, AC022075.1, AC020928.1 and LINC02076 exhibited significant difference between normal and tumor tissue in most types of cancer." (PMID 36530992, 2022).
LINC02076 also shares sentences with these, for which no sentence is quoted: tumor (1 paper).